IDH1 (isocitrate dehydrogenase (NADP(+)) 1)
Diseases named in the same sentence as IDH1 in open-access papers (continued):
Sharing a sentence is not in itself a finding about the gene and the disease.
glioma (continued). "Two independent groups found that IDH1 mutations in low-grade gliomas were associated with significant improved overall survival, whereas others could not find any significant association." (PMID 26858939, 2016). "In addition to these approaches, Boisselier and colleagues demonstrated evidence of principle in detection of IDH1 mutations from the plasma of patients with mutant glioma." (PMID 26858939, 2016). "Efforts such as The Cancer Genome Atlas (TCGA) have comprehensively cataloged the litany of somatic alterations occurring in glioblastoma and lower grade gliomas, leading to discoveries such as the importance of IDH1 mutations in the development of a low-grade glioma and secondary glioblastoma." (PMID 27556016, 2016). "Compound 18 exhibited in vivo antitumor activity in a mouse xenograft model of IDH1 mutated glioma." (PMID 27316347, 2016). "Similarly, mRNA for mutated form of IDH1/2 gene and mRNA for abnormal C-myc gene were observed in EVs circulating in blood of glioma and medulloblastoma patients, respectively." (PMID 27199663, 2016). "In this study, we developed a novel immuno-wall device to detect the IDH1-R132H mutation in glioma." (PMID 27877908, 2016). "Indeed, seeing that IDH1 mutations are specific to gliomas, this antibody can be used to help differentiate between diffuse gliomas and areas of reactive gliosis." (PMID 26858939, 2016). "The methylation of both promoters always occurred as a secondary event in the recurrent lesion, so our finding supports the hypothesis that IDH1 mutation is the primary event in glioma carcinogenesis." (PMID 26865861, 2016). "Nevertheless, gliomas with mutated IDH1/2 gene have better prognosis than the others." (PMID 27462201, 2016). "In this study, using immunohistochemistry, we analysed the ATRX expression status in a large series of gliomas in order to evaluate 1) the predictive potential of ATRX for IDH1/2 and H3F3A mutations and LOH 1p/19q status, 2) the optimal interobserver-reliant cut-off point for ATRX loss." (PMID 27311324, 2016). "Since glioma and leukemia cells harboring mutations in IDH1 or -2 cannot be maintained in culture, previous studies in these tumor types used artificial models to study the role of IDH1/2 mutations." (PMID 25895133, 2015). "Moreover, in IDH1 mutation/1p19q intact gliomas subjected to TCGA, there was increase tendency of copy number loss with WHO grade (4.3%, 10.7% and 25.0% in grade 2, 3, and 4, respectively)." (PMID 26524630, 2015). "Evaluation of EGFR amplification and TERTp mutation in a background of wild-type IDH1/2 in lower-grade gliomas could help to identify aggressive tumors with seemingly low grade histology, facilitating a more precise prognostic estimation." (PMID 26369702, 2015). "Besides these patients with IDH1/2 mutation, 3 other patients with primary glioma benefited from galunisertib." (PMID 25529192, 2015). "Therefore, the predictive role of IDH1 mutation in WHO grade II gliomas is controversial and remains to be established." (PMID 26115094, 2015). "Therefore, we combined a CGH analysis with the IDH1 mutation status to propose the genetic subgrouping of gliomas." (PMID 26558387, 2015). "We studied if combination genetic signature potentially stratifies lower-grade gliomas better than histology by investigating 214 lower-grade gliomas for IDH1/2 and TERTp mutations, 1p/19q codeletion and EGFR amplification as to their impact on prognostication." (PMID 26369702, 2015).
glioma (continued). "The clinical significance of isocitrate dehydrogenase 1 (IDH1) point mutation in gliomas was first reported in 2008, the overall survival (OS) of glioblastoma patients with IDH1-mutated glioblastoma was demonstrated to be significantly longer than that of patients with wild-type IDH1 glioblastoma." (PMID 26558387, 2015). "The mutation in IDH1 gene is widely associated with good prognosis of glioma patients." (PMID 26370624, 2015). "Mutation in IDH1 is observed in ∼80% of grade 2 and 3 gliomas and secondary GBM." (PMID 26496030, 2015). "In comparison with IDH1/2 mutations being widely considered a key development in the early stage of astrocytic tumors, increasing Ki-67 expression is considered the terminal event in glioma progression." (PMID 26338964, 2015). "The alterations in genetic regulatory mechanisms may be the key factor for the major phenotypic changes in IDH1 mutated gliomas." (PMID 26524630, 2015). "We also analyzed the role of IDH1(R132H) mutations in the prognosis of low-grade glioma patients." (PMID 26485760, 2015). "In conclusion, this meta-analysis provides more strong evidence that IDH1/2 mutations is an independent prognostic factor for patients with different grades of glioma and that IDH1/2 mutations is associated with improved OS and PFS, especially for patients with WHO grade III and grade II-III." (PMID 26220714, 2015). "Recent studies confirmed that IDH1 mutation is associated with better prognosis in patients with glioma by inducing cell cycle arrest in G1 phase, inhibiting cell proliferation, and reducing invasion ability, by reducing the levels of matrix metalloproteinases MMP2 and MMP9." (PMID 25695077, 2015). "IDH1 mutation has became as a main diagnostic and prognostic biomarker for gliomas." (PMID 27275230, 2015). "IDH1/2 mutations are early and common events in the etiopathology of astrocytomas, oligodendrogliomas, and oligoastrocytomas, and they are associated with increased DNA methylation, and termed the glioma-CpG island methylator phenotype (G-CIMP)." (PMID 26338964, 2015). "Mutated IDH1 is a common feature in lower grade gliomas and secondary GBMs." (PMID 25790191, 2015). "Therefore, we used Kaplan–Meier curves to evaluate the outcome of 703 patients with glioma following stratification by IDH1/2 mutation status." (PMID 26338964, 2015). "Moreover, G-CIMP was tightly correlated with IDH1 mutation, which was recently identified as an important diagnostic and prognostic molecular biomarker of human glioma and believed to be sufficient to establish G-CIMP." (PMID 25669971, 2015). "Furthermore, in adult gliomas, IDH1 mutations were found to be associated with ATRX mutations and alternative lengthening of telomeres (ALT)." (PMID 26175967, 2015). "Recent studies suggested that mutations in the gene encoding for cytosolic NADP+ dependant IDH1 (isocitrate dehydrogenase 1) might occur after the formation of a low-grade glioma and direct the progression of the tumor to a glioblastoma." (PMID 27275230, 2015). "Molecular characteristics, including methylation of O6-methylguanine-DNA methyltransferase (MGMT) promoter, isocitrate dehydrogenase 1 or 2 (IDH1/2) gene mutations, or 1p/19q chromosomal loci deletion, are currently used to genetically classify glioma patients." (PMID 25695077, 2015). "In gliomas, IDH1/2 mutations are associated with active Hh signaling." (PMID 25895133, 2015). "IDH1 (isocitrate dehydrogenase 1) mutation might be encounter in the low grade glioma and directs the progression of the tumor to a higher grade." (PMID 27275230, 2015). "A high level of 2-HG has been associated with missense mutations in IDH1 or IDH2 in glioma and several other tumor types and may be an effector of tumor cell dedifferentiation." (PMID 25091696, 2014). "Moreover, IDH1 mutations and 2-HG production were identified to be sufficient steps in the process leading to glioma hypermethylator phenotype." (PMID 24511544, 2014).
glioma (continued). "Including data from a previous study and on ongoing routine analysis of all diffuse astrocytoma and oligodendroglioma in the Department of Neuropathology at the University Heidelberg, the present series of IDH1 mutated gliomas comprises tumors from 1,976 patients." (PMID 24529257, 2014). "Our PAM classified IDH1 mutated gliomas with a sensitivity of 95.65% and specificity of 92.41%." (PMID 25277177, 2014). "The aberrant function of mutated IDH1 is the conversion of alpha-ketoglutarate to the novel oncometabolite 2-hydroxyglutarate (2-HG), which leads to genome-wide epigenetic changes in human gliomas." (PMID 24511544, 2014). "Recent meta-analysis also confirmed the prognostic role of IDH1/2 mutations in gliomas." (PMID 24511544, 2014). "Mutations in IDH1 are a common and early event in low grade glioma, they are present in secondary GBM and may cause the G-CIMP phenotype." (PMID 24984002, 2014). "Several studies have confirmed that IDH1 is mutated in approximately 60–80% of diffusely infiltrating gliomas (WHO Grade II and III) and in secondary GBMs, which may derive from them." (PMID 24716189, 2014). "We determined the levels of D-2-hydroxyglutarate in glioma tissues with IDH1 mutations." (PMID 24529257, 2014). "From this study, it may be concluded that IDH1 mutation improves prognosis in glioma patients by altering the cell cycle, inhibiting cell proliferation and downregulating cell invasion ability." (PMID 24520288, 2014). "Although seminal work involving IDH1 mutations and the onco-metabolite 2-HG have been identified in low-grade glioma no clear metabolic pathways specific to aggressive high-grade glioma have yet been described." (PMID 25167383, 2014). "IDH1 mutation may represent a new gene subtype of glioma and be an effective target for tumor therapy." (PMID 24520288, 2014). "In summary, Rab27a expression was significantly associated with grade progression and poor prognosis in all glioma grades, including mesenchymal and G3 subtype and wild-type IDH1, suggesting Rab27a as a novel biomarker with potentially important therapeutic implications." (PMID 24587032, 2014). "As glioma patients with mutated IDH1 have a low capacity for degrading various components of the extracellular matrix, surgery may result in increased opportunity for invasion of glioma cells." (PMID 24520288, 2014). "There is reason to believe that glioma patients with mutated IDH1 may have a better prognosis due to blockage of the cell cycle and inhibition of cell invasion ability." (PMID 24520288, 2014). "The present study focused on the biological changes induced by IDH1 mutation in glioma cells." (PMID 24520288, 2014). "IDH1/2 mutations are a well-established molecular feature of gliomas." (PMID 24722048, 2014). "Given the background genes previously discovered in glioma, we hypothesize TERT promoter and IDH1/2 mutations as the major driver genes that are consistently found in low-grade and high-grade adult gliomas." (PMID 24722048, 2014). "However, in the present study, IDH1 mutation induced changes in the biological behavior of glioma cells and in the mechanism of tumorigenesis." (PMID 24520288, 2014). "The data from the Sanger Institute Cancer Genome Project-Catalogue of Somatic Mutations in Cancer revealed the presence of IDH1 mutations in more than 32% of central nervous system tumors, 23% of bone tumors, 8% of biliary tract tumors, 6% of thyroid cancer, and many other tumor types." (PMID 24511544, 2014).
glioma (continued). "A significant proportion of low grade gliomas (>85%) and a smaller proportion of glioblastomas contain mutations in IDH1 or IDH2, which have been shown to associate with a specific hypermethylated phenotype and predict better overall survival for those patients." (PMID 24202321, 2013). "In intermediate grade gliomas, IDH1 mutation is found in over 70% of tumors." (PMID 24077826, 2013). "Whole exome sequencing of GBMs revealed frequent mutations at the position 132 arginine residue in the catalytic domain of Isocitrate Dehydrogenase 1 (IDH1) of progressive gliomas and targeted sequencing found additional mutations in the mitochondrial family member IDH2." (PMID 24077805, 2013). "Similarly, in vivo models are difficult to propagate and as a result, preclinical glioma models carrying the IDH1 or IDH2 mutation are scarce." (PMID 24252742, 2013). "IDH1 mutation alone is enough for the development of the glioma hypermethylate phenotype." (PMID 23516171, 2013). "Classical molecular markers with clinical implications such as MGMT promoter methylation, 1p 19q codeletion, and IDH1 mutations are known favorable prognostic markers in gliomas, with MGMT promoter methylation being the only potential predictive marker for alkylating chemotherapy in GBM." (PMID 24202336, 2013). "The high frequency (>80%) of IDH1/2 mutations in secondary glioblastomas which have progressed from low-grade gliomas, suggests that these tumors share a common progenitor cell population which through sequential molecular evolution gives rise to the IDH1 mutant glioblastoma." (PMID 24202337, 2013). "The dependency of our predictor classification to commonly used grade II/III glioma prognostic factors (1p19q loss of heterozygosity, IDH1 gene mutation and EGFR gene amplification) was analyzed using the NL validation cohort for which these molecular data were available." (PMID 23805239, 2013). "In conclusion, this method could be successfully implemented in the diagnostic work-up for various tumors known to harbor IDH1/2 mutations (e.g. myeloid malignancies, gliomas, etc.)." (PMID 24098815, 2013). "In addition, in patients with AML and glioma we focus on the associations between IDH1/2 mutations and clinical, morphologic, cytogenetic, and molecular characteristics." (PMID 23847760, 2013). "Mutation in the IDH1 or IDH2 genes occurs frequently in gliomas and other human malignancies." (PMID 24077826, 2013). "IDH1 R132 mutations are gain-of-function, causing the enzyme to produce 2-hydroxyglutarate (2-HG) and IDH1-mutant tumors display distinct DNA methylation profiles with global hypermethylation, termed a glioma-CpG island methylator phenotype (G-CIMP)." (PMID 23417712, 2013). "IDH1/2 mutations are common in several cancers, including gliomas." (PMID 24202321, 2013). "Thus, IDH1 mutations are thought to play an important role in the early phase of glioma development." (PMID 24160898, 2013). "Regional frequencies of 1p/19q co-deletion and IDH1/2 mutation in glioma subsets." (PMID 22427879, 2012). "Also, IDH1- mutations were detected in high frequencies in low grade gliomas of astrocytic and oligodendroglial differentiation identifying IDH1- mutations as a common early and important event during tumor development." (PMID 22844452, 2012). "In 280 gliomas, the mean global incidence of IDH1/2 mutation was 58.6%." (PMID 22427879, 2012). "Moreover, we did not observe IDH1/2 mutation in 10 DIPG while in adult proneural gliomas IDH1 mutations are frequent." (PMID 22389665, 2012). "Gliomas containing IDH1 R132 mutations have marked elevations of 2HG." (PMID 21326614, 2011). "However, IDH1 mutations were detected at much higher frequencies (over 70%) in grade II and II gliomas.; Mutations in the homologous IDH2 gene were also identified (around 5%), predominantly in oligodendroglial tumors." (PMID 24212656, 2011).
glioma (continued). "IDH1 mutations seem to have a significant role in glial tumours." (PMID 21326241, 2011). "In this paper, we described obstacles in culturing glioma cells with IDH1 mutations." (PMID 21326241, 2011). "In glioma IDH1 mutations are associated with a CpG methylator phenotype." (PMID 22046342, 2011). "In contrast to this, all of these mutants confer 10- to 100-fold higher 2HG production to cells, and glioma tissues containing IDH1 R132 or IDH2 R172 mutations contain high levels of 2HG compared to glioma tissues without IDH mutations (54.4 vs. 0.1 mg 2HG/g protein)." (PMID 21326614, 2011). "A follow-up study analyzed IDH1 codon 132 mutations in a large series of 685 brain tumors comprising all major glioma subtypes and reported IDH1 mutation frequencies of up to 70% in diffuse astrocytomas, while virtually no mutations were detected in pilocytic astrocytomas." (PMID 19333441, 2009). "The enzyme produced by IDH1 is pivotal in a key stage of the citric acid cycle; its mutation can trigger the abnormal accumulation of 2-hydroxyglutarate, resulting in the CpG island methylation phenotype and heightened histone methylation in glioma, which are deemed as critical early events in LGG." (PMID 40276502, 2025). "Notably, IDH1/2 mutations induce abnormal accumulation of 2-hydroxyglutarate (2-HG), which disrupts epigenetic modifications and promotes metabolic reprogramming, serving as a hallmark of low-grade gliomas." (PMID 40661781, 2025). "Importantly, we showed the spatial heterogeneity of IDH1 mutation in human glioma tissue." (PMID 40171868, 2025). "However, the mutated IDH1 R132H enzyme produced the metabolite D-2-hydroxyglutarate (2-HG), which competitively inhibited many α-KG-dependent dioxygenases, leading to histone dysregulation and abnormal angiogenesis, and ultimately inducing glioma." (PMID 41381536, 2025). "A study published in the Journal of Clinical Neuroscience used human brain tumor samples and demonstrated that elevated 2-HG could be used as a biomarker of the IDH1/2 mutation status in gliomas, which would distinguish glioblastomas from astrocytomas and oligodendrogliomas." (PMID 41002991, 2025). "Alongside conventional contrast-enhanced imaging, inclusion of FLAIR sequences to the routine glioma MRI protocol has been advocated to improve the diagnostic accuracy for both intracranial and spinal leptomeningeal metastasis, particularly in patients with IDH-1 wildtype astrocytoma." (PMID 41008823, 2025). "Therefore, the use of IDH1 mutation status as a prognostic biomarker of tumor molecular evolution has allowed easier and more accurate risk stratification of glioma patients and could be a key tool to improve their personalization of treatments." (PMID 38172718, 2024). "Thus, the oncogenic mutations in the cytosolic IDH (IDH1) have been detected in some cancerous neoplasms, namely, acute myeloid leukemia and poorly differentiated and secondary glioblastoma, cholangiocarcinoma, chondrosarcoma, and glioma." (PMID 39590666, 2024). "Moreover, our results also indicated that reduced OGDH expression can promote the differentiation of glioma cells, while IDH1 mutations impeded the differentiation of glioma cells with low OGDH by reducing the accumulation of α-KG and increasing glutaminolysis." (PMID 39872214, 2024). "Interestingly, IDH1 mutations cause changes in the expression of SCD1 in glioma cells." (PMID 38509672, 2024). "Moreover, patients with IDH1 wild-type high-grade gliomas harboring BRAF or NF1 mutations and receiving trametinib monotherapy or in combination with dabrafenib had longer progression-free and overall survival than patients who did not receive genotype-matched targeted therapy." (PMID 38481999, 2024). "Therefore, α-KG analogs can be used as treatments for gliomas with IDH1 mutations." (PMID 38622131, 2024).